KRT15 (keratin 15)
Diseases named in the same sentence as KRT15 in open-access papers (continued):
Sharing a sentence is not in itself a finding about the gene and the disease.
radicular cysts (2 papers, 2020 to 2022). "The expression of cyclooxygenase-2 (COX-2) and Keratin-15 (K15) in radicular cysts (RCs) is poorly understood." (PMID 35419179, 2022). "Key words:Cyclooxygenase, COX-2, Keratin-15, K15, Radicular cyst." (PMID 35419179, 2022).
skin squamous cell carcinoma (2 papers, 2013 to 2025). A carcinoma arising from the squamous cells of the epidermis. "Overexpression of KRT15 (cytokeratin) was seen in colorectal and squamous cell skin cancers, but its low expression in BC (as seen here) has been significantly associated with poor prognosis." (PMID 41048341, 2025).
staphylococcus aureus infection (2 papers, 2018 to 2020). An infectious process in which the bacteria Staphylococcus aureus is present. "Intriguingly, two up-regulated genes DHFR and KRT15 at mRNA and protein levels were related to one carbon metabolism and staphylococcus aureus infection, respectively." (PMID 29843597, 2018).
adenoma (1 paper, 2021). A neoplasm arising from the epithelium. "Hence, loss of Apc in Krt15+ cells—a heterogeneous population, encompassing Lgr5+ and Lgr5− cells, spanning the crypt base as well as the TA zone—leads to adenomas that occasionally progress to invasive adenocarcinomas." (PMID 33673710, 2021). "It remains to be determined whether the coexistence of adenomas and adenocarcinomas—frequently a feature of human polyposis syndromes—reflects tumour initiation from distinct differentially localized subsets of Krt15+ cells." (PMID 33673710, 2021).
cholesteatoma (1 paper, 2014). A pathologic process characterized by the proliferation of keratinizing squamous epithelium resulting in the accumulation of keratin and cells in the middle ear and/or mastoid. "Other keratins had increased levels of expression in non-cholesteatoma tissues: KRT76, 79 (Tympanic membrane), KRT15 (EACS), and KRT7, 8, 18, 19 (Mucosa)." (PMID 25093596, 2014).
colon cancer (1 paper, 2022). "Several studies have shown that the expression of keratins, such as KRT17 and KRT15, is higher in colon cancer tissues than in normal colonic epithelial tissues, and increased concomitantly as the grade of T staging progresses." (PMID 36217128, 2022).
emphysema (1 paper, 2023). "Krt15−/− CS mice developed severe inflammatory cell infiltration, airway remodeling, and emphysema." (PMID 38007424, 2023).
head and neck squamous cell carcinoma (1 paper, 2024). A squamous cell carcinoma that arises from any of the following anatomic sites: lip and oral cavity, nasal cavity, paranasal sinuses, pharynx, larynx, and salivary glands. "Notably, a Krt15+/Col3a1+ cell type with epithelial‐mesenchymal features may play a crucial role in head and neck squamous cell carcinoma." (PMID 39245637, 2024).
Hyperglycemia (1 paper, 2023). An increased concentration of glucose in the blood. "At 4 and/or 8 weeks of hyperglycemia, different cohorts of animals were euthanized, eyes removed and processed for assessment of limbal morphology, expression of OGF, OGFr, cytokeratin 15, a marker for limbal cells, and Ki-67, a marker of proliferation." (PMID 37304310, 2023).
Hypertension (1 paper, 2024). The presence of chronic increased pressure in the systemic arterial system. "Meanwhile, NONRATG012674.2, which is overexpressed in the high salt sensitivity group, could interact with key hypertension genes like Anxa8, Hspa5, and Krt15, with Hspa5 being part of the HSP70 family associated with hypertension and inflammation." (PMID 38791545, 2024).
keloid (1 paper, 2022). An irregularly shaped, elevated mark on the skin caused by deposits of excessive amounts of collagen during wound healing. "Most keratins were downregulated in keloids, including KRT10, KRT14, KRT15, KRT19, KRT1, KRT77, and KRT5." (PMID 35435317, 2022).
lymphoma (1 paper, 2017). A malignant (clonal) proliferation of B- lymphocytes or T- lymphocytes which involves the lymph nodes, bone marrow and/or extranodal sites. "In this situation, the first pair of genes entering the model are BCL8 and KRT15, where BCL8 is known to be associated with lymphoma." (PMID 29100492, 2017).
nevus (1 paper, 2020). Nevus (or naevus, plural nevi or naevi, from nævus, Latin for "birthmark") is the medical term for sharply circumscribed[1] and chronic lesions of the skin or mucosa. "It suggested that significantly elevated FABP5, IVL, KRT6A, KRT15, KRT16, and TIMP2 proteins expressed in the CM than in the nevus tissues." (PMID 32934956, 2020). "Next, to validate differential expressions of six prognostic hub genes between CM tissues and nevus tissues, we performed IHC analysis and found significantly elevated FABP5, IVL, KRT6A, KRT15, KRT16, and TIMP2 protein expressions in the CM than in the nevus tissues." (PMID 32934956, 2020).
oral squamous cell carcinoma (1 paper, 2023). "Moreover, transcriptional up-regulation of KRT14, and down-regulation of KRT15 and KRT19 was observed in oral squamous cell carcinoma (OSCC)." (PMID 36949761, 2023).
periodontitis (1 paper, 2025). An acute or chronic inflammatory process that affects the tissues that surround and support the teeth. "The expression of KRT15, a basal epithelial marker, clearly delineated the boundary between the epithelium and the lamina propria, while PTPRC, a pan-immune marker, revealed the spatial infiltration of immune cells in periodontitis." (PMID 41358003, 2025).
prostate adenocarcinoma (1 paper, 2022). "Therefore, we next assessed the correlation of KRT15 and KRT19 expression with overall survival in the Metastatic Prostate Adenocarcinoma (SU2C/PCF Dream Team) patient cohort." (PMID 36033462, 2022).
uterine diseases (1 paper, 2020). "Conditional loss of EZH2 in the uterus upregulated genes associated with uterine diseases, including keratin 5 (Krt5), keratin 15 (Krt15), the maternally-imprinted gene- H19, leucine-rich repeat-containing G-protein-coupled receptor 5 (Lgr5), and cell division cycle associated 5 (Cdca5)." (PMID 33732505, 2020).
vasculitis (1 paper, 2020). "Autoantibodies against native KRT15 were found in patients suffering from RA with secondary vasculitis." (PMID 32486012, 2020).
tumor (54 papers, 2003 to 2026). "IHC and cytological experiments confirmed upregulation of KRT15 in HPV+HNSCC tumor cells, which also showed high expression of cancer stem cell marker genes." (PMID 41462011, 2025). "The genetic knockout of Wls in hair follicle Keratin 15+ cells results in reduced tumor growth, incidence, and reduced SOX2-positive CSC cell numbers in the skin." (PMID 37686421, 2023). "In HER2low TNBC group, the fate 1 branch was predominantly associated with module 2 genes (PTN, KRT15, S100A8, etc.)which suggested the tumor harbored the features of apoptosis, migration and metabolism." (PMID 36998014, 2023). "Our experimental results using genetically engineered mice further demonstrate the potential benefit of PPI treatment in tumor initiation from tumor-competent Krt15+ foregut basal progenitors." (PMID 31110179, 2019). "This study demonstrates the association of gastric acid stress with Cyclooxygenase-2-dependent tumor formation originating from tumor-competent Krt5+/Krt15+ foregut basal progenitor cells." (PMID 31110179, 2019). "Taken together, this study demonstrates the significant contribution of physiological acid stress as a co-promoting factor in foregut tumor initiation from tumor-competent Krt5+/Krt15+ basal progenitor cells." (PMID 31110179, 2019). "Here, the authors show that gastric acid stress stimulates tumour formation from a defined tumour-competent Krt5 + /Krt15 + foregut basal progenitor cell population." (PMID 31110179, 2019). "Tumorigenesis from Krt15+ foregut progenitors requires squamous epithelial-specific Cox-2 expression for efficient tumor formation." (PMID 31110179, 2019). "Down-regulation of KRT15 in tumour metastases (relative to primary tumours) is also common to many solid human cancers." (PMID 30566430, 2018). "Our results revealed that, compared to para-cancerous tissues, the expression levels of SLC14A1, NEFH, MSMB, KRT23, and KRT15 were significantly downregulated in PCa tumor tissues, while ARHGEF38 expression was notably upregulated, consistent with our initial predictions." (PMID 40260298, 2025). "To test this hypothesis in humans, we first examined KRT15 expression (basal marker) in tumour cells and found that as predicted, KRT15 was highly expressed in tumour cells." (PMID 35608199, 2022). "Several genes within the S100 family were increased in tumor cells including a tumor-enriched cluster expressing S100A2 together with KRT15 and COL17A1 which are notable as markers of a quiescent stem/progenitor cell population in the most basal layer of the human esophagus." (PMID 36253784, 2022). "Remarkably, while the majority of Lgr5+ subsets are exquisitely sensitive to DNA damage, Krt15+Lgr5+ cells are radioresistant and may thus survive to spawn tumours post injury." (PMID 33673710, 2021). "Alternatively, we hypothesized that the regional microenvironment may significantly influence tumor initiation from tumor-competent Krt15+ progenitors." (PMID 31110179, 2019). "Furthermore, tdTomato lineage tracing revealed that tumor cells preferentially arise from the Krt15+ cells located in this adjacent region." (PMID 31110179, 2019). "KRT15 transcripts were higher in superficial versus invasive tumours." (PMID 24260555, 2013).
tumor (continued). "It is interesting to note that reduced expression of keratin 15 (KRT15) is associated with increased expression of the translation factor EIF2S1 in the prediction model for increased elastase, which in turn predicts a lower stage tumor." (PMID 19455237, 2007). "Of note, higher levels of cytokeratin 15 are expressed in other forms of neoplasia." (PMID 19455237, 2007). "Differential gene expression analysis demonstrated that Tum_1 tumor cells predominantly expressed basal cell marker genes such as KRT14, KRT5, and KRT15, and exhibited high levels of genes related to cell adhesion, including ITGB4 and ITGA6." (PMID 40470730, 2025). "In women KRT15 has been suggested as a marker to differentiate between DCIS and invasive BC, with a correlation of KRT15 expression with histological grade, tumor node stage and tumor node metastasis stage." (PMID 39696035, 2024). "KRT15 was also mainly restricted to SCC, with variable distribution and intensity among different SCCs and among different areas of the same neoplasm." (PMID 31809668, 2020). "FABP5, IVL, KRT6A, KRT15, KRT16, and TIMP2 expression profiles suggested relatively significant elevated expression in tumor tissues compared with the corresponding normal tissues." (PMID 32934956, 2020). "Moreover, KRT15, CALML5, and S100A2 have been described as having stem cell functions and EMP regulation, suggesting both tumor-promoting and tumor-suppressive roles." (PMID 39225101, 2024). "Comparing the bulk transcriptome profiles of the TD and nonTD patients, the TD patients exhibited upregulation of keratins (KRT81, KRT6B, KRT15, KRT5) and kallikreins (KLK5, KLK6, KLK7), indicating active extracellular matrix (ECM) remodeling and tumor expansion." (PMID 39664386, 2024). "Our comparison of two DCIS regions in Sample #1 reveals reduced myoepithelial markers KRT15, KRT23, and ALDH1A3 and increased invasive markers in DCIS #2 which could indicate a higher grade tumor." (PMID 38114474, 2023). "KRT15 marked a subset of KRT14high tumor nests, LHX2 marked the nucleus of cells along the outer periphery of KRT14high tumor nests, and ACTA2 marked the outer periphery of KRT14low tumor nests." (PMID 35687691, 2022). "However, if a tumor cannot be diagnosed based only on histological features, staining with positive markers, including CK17 (cytokeratin 17), CK15 (cytokeratin 15), CK5/6 (cytokeratin 5/6), and p63, should be supportive." (PMID 34064849, 2021). "However, we identified a small triple positive (ERBB2 + /ESR1 + /PGR + (HER2 + /ER + /PR +)) DCIS region located in proximity to adipocytes which consisted of a predominantly DCIS #2 tumor epithelium without a KRT15+ myoepithelial cell layer." (PMID 38114474, 2023). "Notably, several basal progenitor state factors (Hoxc13, Pax9, Gli2, Krt15) displayed paradoxical downregulation, indicating that EY-driven transcriptional changes do not reflect a physiologic OEPC cell state, but rather constitute a unique cellular state related to tumor initiation." (PMID 37961717, 2023).
cancer (29 papers, 1996 to 2026). A tumor composed of atypical neoplastic, often pleomorphic cells that invade other tissues. "Among these genes, seven proteins (MAP2K1, FERMT2, HMGB2, FAF2, STK26, THRAP3, and KRT15) showed significant differences between carcinoma and adjacent tissues (TCGA-HNSC database)." (PMID 39319867, 2025). "We further investigated the expression and distribution of proliferation-related (CDK4, MKI67) and cancer-related epithelial (KRT15, CD24) cell marker genes among each cluster." (PMID 36811599, 2023). "COL17A1, KRT15, KRT17, S100A2, SFN, which have been shown to assume oncogenic roles in various cancers, were among the highly changed genes and positively correlated with p63 expression." (PMID 38012140, 2023). "In fact, EGFR was part of a cluster of dysregulated genes and enriched gene sets in the FIR20 cells that define the basal breast (cancer) subtype (LAMC2, TRIM29, COL17A and cytokeratin genes (KRT6, KRT7, KRT13, KRT15))." (PMID 35579852, 2022). "KRT15, KRT19 and KRT8 were amplified and the expression were significiantly higher in the AA cancer cell lines compared to EA cell lines." (PMID 36033462, 2022). "We further applied immunostaining to early invasive cancer tissues and found that the number of KRT13+ and KRT15+ cells had decreased." (PMID 35608199, 2022). "In our study, high expression of both KRT15 and KRT19 in low-risk ERG fusion negative patients was associated with the enrichment of common cancer-associated gene signatures, especially KRAS." (PMID 36033462, 2022). "KRT15 and KRT19 are also downregulated in OSCC, and the expression levels of the remaining KRT15 and KRT19 represent differentiation and the invasive potential of the cancer, respectively." (PMID 27512993, 2016). "In addition to cancer regions, sample 2 could also distinguish regions of breast ductal epithelial cells (cluster 6) with high expression levels of PTN, RGS2, CLU, and KRT15." (PMID 34799559, 2021).
infection (13 papers, 2012 to 2025). The state of being infected such as from the introduction of a foreign agent such as serum, vaccine, antigenic substance or organism. "The infection mainly affected the expression of ck15 (encoding cytokeratin 15), whose expression was downregulated seven-fold in both CyHV-3 challenged groups, which coincided with a 32- and 49-fold increase in the expression of inos, indicating inflammation." (PMID 35173716, 2022). "We found that, compared to infection with the parental pOka strain, the vOka strain has only a modest effect on KRT15 levels even when cells were infected with the highest MOI possible (MOI = 0.2)." (PMID 39385182, 2024). "To evaluate how vOka affects the upregulation of KRT15, we infected N/TERT keratinocytes with the pOka or vOka strains at equal levels of virus and monitored KRT15 levels post-infection." (PMID 39385182, 2024). "Some up-regulated genes at 21 dpi (e.g., Ltf, Cxcl9, Pglyrp1, Prg2, Cxcl13, Cxcl3, Ccl9, Ccl19, Krt5, Krt14, Krt15, Krt17, and Slpi) were also identified in a previous infection study by using H1N1(PR8)." (PMID 38005876, 2023). "We observed significant increase in KRT15 mRNA levels at 24 and 48 h hours post-infection." (PMID 39385182, 2024). "Other observed changes in cytokeratin expression which do not usually form part of a blistering signature include the upregulation of KRT15 and KRT19 which are associated with stem cells in adnexal skin compartments, a region which histologically is positive for VZV early on in infection." (PMID 24497829, 2014). "At these conditions only one gene was detected as significantly up-regulated after infection, NLRP2, and four genes were down-regulated (ALDH3A1, CXCL8, IL1R2, KRT15)." (PMID 34785679, 2021). "As expected, KRT15 expression was upregulated in the pOka-infected cells, whereas there was no significant change in KRT15 levels between the vOka infections and uninfected cells, even when vOka was used at double the MOI than pOka )." (PMID 39385182, 2024). "While shKRT15 #1 and #2 prevented the upregulation of KRT15 post-infection, shKRT15 #3 failed to do so and 96 h post-infection KRT15 upregulation was similar to that found in the control cells." (PMID 39385182, 2024).
adenocarcinoma (3 papers, 2020 to 2023). A common cancer characterized by the presence of malignant glandular cells. "In addition, epithelial cells of patient #6 consisted of a group of NE cells (cluster 4, expressing ASCL1, CHGA, and CHGB), a group of basal cells (cluster 8, expressing KRT5, KRT14, and KRT15) as well as the remaining ARhigh luminal cells, presenting mixed features of both adenocarcinoma and NEPC." (PMID 33328604, 2020).
genetic disease (1 paper, 2026). "At present, therefore, KRT15/K15 stands out among the main epidermal keratins given a lack of known involvement in a human genetic disease." (PMID 41511042, 2026).
lung (1 paper, 2020). "Materials and methods: We compared the usefulness of six conventional (CK5/6, p40, p63, CK7, TTF1, and Napsin A) and three novel (PKP1, KRT15, and DSG3) markers to distinguish between lung SCC and AC in 85 small biopsy specimens (41 ACs and 44 SCCs)." (PMID 31809668, 2020).
KRT15 also shares sentences with these, for which no sentence is quoted: Kaposi's sarcoma (4 papers); oral lichen planus (3); skin tumors (3); trichoblastoma (3); AIDS (2); androgenetic alopecia (2); diabetes (2); gastric cancer (2); odontogenic cyst (2); viral infection (2); actinic keratosis (1); acute myeloid leukemia (1); ameloblastoma (1); asthma (1); bacterial infections (1); benign tumour (1); bladder tumours (1); breast tumors (1); bronchiolitis obliterans (1); co-infection (1); COVID-19 (1); cutaneous melanoma (1); dacryoadenitis (1); ductal carcinoma in situ (1); dysplasia (1); epidermolysis bullosa simplex (1); Fibroadenoma (1); fibrosarcoma (1); heart failure (1); hepatitis B (1).
A further 27 diseases each share a sentence with KRT15 in 1 paper.